ANK3 (ankyrin 3)
Diseases named in the same sentence as ANK3 in open-access papers (continued):
Sharing a sentence is not in itself a finding about the gene and the disease.
Cognitive impairment (5 papers, 2014 to 2025). Abnormal cognition is characterized by deficits in thinking, reasoning, or remembering. "Lamotrigine was added as a therapeutic option to combat the patient's cognitive deficits and ongoing agitation and stress; it was chosen for its mechanism involving sodium channels as a potential modifier of the patient's ANK3 variation." (PMID 24744941, 2014).
Ataxia (4 papers, 2012 to 2026). Ataxia refers to impaired coordination of voluntary muscle movement. "Our findings support a recognizable NDD with non‐progressive cerebellar ataxia linked to biallelic ANK3 pLOF variants." (PMID 40879451, 2025). "In conclusion, our findings define a novel autosomal recessive neurodevelopmental syndrome with non‐progressive cerebellar ataxia, refining the phenotypic spectrum of ultra‐rare recessive ANK3‐related disorders." (PMID 40879451, 2025). "This may be due to the confounding factor of ataxia in Ank3-1bKO/KO mice, making it difficult for Ank3-1bKO/KO mice to engage in prolonged bouts of coordinated grooming and digging movements." (PMID 38123552, 2023). "Digging may provide a better measure of repetitive behaviors in Ank3-1b mice because, unlike grooming, it does not require animals to balance on their hind paws, which may be more difficult for Ank3-1bKO/KO mice due to their mild ataxia." (PMID 38123552, 2023). "The initial characterization of Ank3−/− mice that completely lack brain-specific isoforms noted a progressive early-onset ataxia due to impaired action potential firing at axon initial segments (AIS) of Purkinje neurons in the cerebellum, which is important for motor control." (PMID 23025490, 2012).
mental disorder (4 papers, 2015 to 2024). A disease that has its basis in the disruption of mental process. "Our results suggest that ANK3 expression levels moderate the association between specific types of childhood trauma and affective traits in mental disorders." (PMID 37620394, 2023). "Here we investigated if ANK3 mRNA levels influence the relationship between childhood trauma experiences and clinical characteristics in mental disorders." (PMID 37620394, 2023). "We found that ANK3 mRNA levels moderated the relationship between specific types of childhood traumas and affective episodes in severe mental disorders." (PMID 37620394, 2023). "In summary, our study points to ANK3 mRNA expression as a biological marker influencing the relationship between childhood trauma experiences and more severe affective clinical traits in severe mental disorders." (PMID 37620394, 2023).
Alzheimer disease (3 papers, 2012 to 2022). A progressive, neurodegenerative disease characterized by loss of function and death of nerve cells in several areas of the brain leading to loss of cognitive function such as memory and language. "However, using an extended and even more recent list of GWAS results from the European Alzheimer’s disease DNA biobank (EADB) project published as preprint reveals several new connections, i.e. for ADAM17 & USP6NL (both miR-129-5p), CTSB & EED (miR-138-5p), and ANK3 & PLEKHA1 (miR-195-5p)." (PMID 36038535, 2022).
mood disorder (3 papers, 2014 to 2022). A cognitive disorder a disturbance in which the person's mood is hypothesized to be the main underlying feature. "Four of the most consistently replicated variants associated with mood disorder occur in genes important for synaptic function: ANK3 (rs10994336), BDNF (rs6265), CACNA1C (rs1006737), and DGKH (rs1170191)." (PMID 24944871, 2014). "A recent study reported that ANK3 is the top gene associated with mood disorders and stress." (PMID 35646694, 2022). "Researchers had also revealed that the expression of ANK3 was increased in expression in the amygdala of a mouse model of mood disorders and stress." (PMID 35646694, 2022). "Carriers of the minor BDNF and ANK3 alleles showed nonsignificant trends toward protective association in controls relative to mood disorder patients (P = 0.047)." (PMID 24944871, 2014).
ovarian carcinoma (3 papers, 2020 to 2025). A malignant neoplasm originating from the surface ovarian epithelium. "Bioinformatic analysis revealed that NDRG1, CYBRD1, and MT2A expressions upregulated and were associated with poor prognosis of ovarian cancer patients in the platinum-based treatment group, whereas upregulation of ERBB4 and ANK3 correlated with improved prognosis." (PMID 38987777, 2024).
post-traumatic stress disorder (3 papers, 2014 to 2023). An anxiety disorder precipitated by an experience of intense fear or horror while exposed to a traumatic (especially life-threatening) event. "Supporting the association of ANK3 with stress-related behaviors, a recent study has linked ANK3 SNPs with both post-traumatic stress disorder and externalizing (a measure identifying adult anti-sociality and substance abuse) in a cohort of military veterans." (PMID 25191280, 2014).
attention deficit-hyperactivity disorder (2 papers, 2017 to 2022). A disorder characterized by a marked pattern of inattention and/or hyperactivity-impulsivity that is inconsistent with developmental level and clearly interferes with functioning in at least two settings (e.g. at home and at school). "In addition, de novo missense mutations in ANK3 have been identified in autistic patients as well as severe cognitive deficits, borderline intelligence, severe attention deficit hyperactivity disorder (ADHD) and sleeping problems." (PMID 28536506, 2017).
channelopathies (2 papers, 2019 to 2024). "Ank3 and Cacna1c, which have been associated with channelopathies and the development of neuropsychiatric disorders, also presented an upregulation in their expression levels." (PMID 38793693, 2024).
colon cancer (2 papers, 2021 to 2025). "A recent study indicated that frameshift mutation in ANK3 (hub in Subnetwork 4) in colon cancer." (PMID 34790220, 2021).
lung carcinoma (2 papers, 2020 to 2025). "Previous studies have shown that ANK3 can promote cell survival by reducing the inhibition of detachment-induced apoptosis, and that ANK3 is a potential therapeutic target for colorectal and lung cancers." (PMID 41174507, 2025).
microphthalmia (2 papers, 2022 to 2023). Congenital or developmental anomaly in which the eyeballs are abnormally small. "It plays an obligatory role in normal lens development, and Ank3 knockout mice develop bilateral microphthalmia and cataracts." (PMID 37118843, 2023). "Knockdown of ank3, bmpr1b, and pdgfaa revealed a coloboma and/or microphthalmia phenotype." (PMID 35034853, 2022).
neuropathies (2 papers, 2021 to 2024). "In summary, our study identified compound heterozygous variations that expand the spectrum of pathogenic ACO2 variants and revealed key mediating molecules, LRP8 and ANK3, between ACO2 mutations and the development of neuropathy." (PMID 39600307, 2024).
polycystic kidney disease (2 papers, 2019 to 2023). A usually autosomal dominant and less frequently autosomal recessive genetic disorder characterized by the presence of numerous cysts in the kidneys leading to end-stage renal failure. "It was discovered that ANK3 is implicated in renal magnesium handling and polycystic kidney disease." (PMID 30941304, 2019). "Currently, the association of the ANK3 gene and kidney diseases in humans is not well documented, however the ANK3 gene is associated with polycystic kidney disease in mice." (PMID 37639939, 2023).
stress-related disorder (2 papers, 2016 to 2023). Stress-related disorders are mental health disorders that are a result of an atypical response to both short and long-term anxiety due to physical, mental, or emotional stress. "Since ANK3 expression can be modified by pharmacological interventions and by long-term lithium use, ANK3 could be seen as a target for drug intervention in individuals with stress-related disorders with neurodevelopmental origin, but more research is needed in this field." (PMID 37620394, 2023).
acute sinusitis (1 paper, 2016). "Specifically, several SNPs mapping to ANK3 are highly represented in both the acute respiratory infection and the chronic sinusitis association results, and variants mapping to ANKS1A were associated with acute sinusitis." (PMID 27508393, 2016).
alcohol withdrawal syndrome (1 paper, 2024). "Since the development of alcohol withdrawal syndrome after abstinence is likely due to alcohol-induced neuronal damage in the brain, genes associated with brain neurons, such as ANK3 and ZNF804A, may have unknown mechanisms of action in alcohol withdrawal syndrome." (PMID 38702695, 2024).
autoimmune disease (1 paper, 2017). A disorder resulting from loss of function or tissue destruction of an organ or multiple organs, arising from humoral or cellular immune responses of the individual to their own tissue constituents. "The random forest classification predicted ZNF804A, ANK3 and DOCK3 that have so far not been connected to SLE or any other autoimmune disease to be risk genes for SLE." (PMID 28740209, 2017).
Becker muscular dystrophy (1 paper, 2022). Becker muscular dystrophy (BMD) is a neuromuscular disease characterized by progressive muscle wasting and weakness due to degeneration of skeletal, smooth and cardiac muscle. "From the identified disease-specific genes, four genes (ANK3, GALK2, ZBTB45 and PLXNA1) were previously reported to be involved in the pathogenesis of DMD and Becker Muscular Dystrophy (BMD), a milder form of DMD." (PMID 35388741, 2022).
bladder cancer (1 paper, 2016). "After discovery and confirmation, five genes MLL, EP400, PRDM2, ANK3 and CHD5 significantly correlated with the recurrence of bladder cancer." (PMID 26625313, 2016). "Additionally, the contribution of specific alterations of EP400, PRDM2, ANK3 and CHD5 to bladder carcinoma recurrence should also be further investigated." (PMID 26625313, 2016).
cerebrovascular diseases (1 paper, 2021). "Variants of ANK3 have not been reported previously to be associated with cerebrovascular diseases." (PMID 34248821, 2021).
geographic atrophy (1 paper, 2022). "The eQTL associated with ANK3 and rs4948258 in RPE3 had a significant interaction between genotype and disease which decreased expression levels in geographic atrophy cell lines." (PMID 35882847, 2022).
glioblastoma (1 paper, 2020). The most malignant astrocytic tumor (WHO grade IV). "TOP2A, COL4A1 and PXDN were significantly upregulated and ANK3, ARRB1 and ANO4 markedly downregulated in glioblastoma compared to controls." (PMID 32962742, 2020).
Insulin resistance (1 paper, 2017). Increased resistance towards insulin, that is, diminished effectiveness of insulin in reducing blood glucose levels. "ANK3 encodes a protein from ankyrin family, and ankyrins have been associated with age dependent adiposity and insulin resistance in a rat model system." (PMID 28264723, 2017).
Lennox-Gastaut syndrome (1 paper, 2020). Lennox-Gastaut syndrome (LGS) belongs to the group of severe childhood epileptic encephalopathies. "Also, a de novo missense mutation within ANK3 is reported in a child with Lennox-Gastaut syndrome." (PMID 33287748, 2020).
liver fibrosis (1 paper, 2025). "Most of the current research on ANK3 has focused on the nervous system, with few studies on liver fibrosis." (PMID 40943308, 2025). "In addition, our study showed, for the first time, that ANK3 expression was increased in human liver samples with liver fibrosis compared with non-fibrotic subjects." (PMID 40943308, 2025).
myeloma (1 paper, 2024). "SERPINE1 (together with ANGPTL4, GDF15, CXCL12, SOX9, HOXB6, and ANK3) was even described as a TA-MSC factor, namely, in mesenchymal stromal cells of the bone marrow that supported myeloma cell growth." (PMID 39011489, 2024).
neuroblastoma (1 paper, 2025). Neuroblastoma (NB) is the most common solid, extracranial childhood tumor. "When the mini-gene was transiently transfected into differentiated mouse neuroblastoma N2a cells, E35a was completely skipped, similar to the splicing pattern of the endogenous Ank3 in non-neuronal cells and tissues." (PMID 41427402, 2025).
nicotine dependence (1 paper, 2019). Physical and psychological dependence on nicotine. "As Hetionet does not include information about smoking, we chose “nicotine dependence” as a proxy.ANK3 is connected to nicotine dependence through several nodes, two of which are particularly noteworthy." (PMID 31372216, 2019).
ocular coloboma (1 paper, 2022). "Novel pathogenic variants in ANK3, BMPR1B, PDGFRA, and CDH4 were identified in 8 unrelated coloboma families." (PMID 35034853, 2022).
oral cancer (1 paper, 2022). "Therefore, further study is needed to elucidate the relationship between these genes (including CDH3 and ANK3) and cancer metastasis in oral cancer cells and tissue." (PMID 35745623, 2022).
prediabetes (1 paper, 2024). "Additionally, we have identified a decrease in the expression of Ankyrin-3 (ANK3) in the prediabetes group compared to normoglycemic individuals." (PMID 39085321, 2024).
progeroid syndrome (1 paper, 2012). A group of rare genetic disorders which mimic physiological aging, making affected individuals appear to be older than they are. "Ankyrin 3 (ANK3) is overexpressed in cells with the progeroid syndrome Hutchinson-Gilford, which is supported by the increase of gene expression with donor age in our research." (PMID 22927939, 2012).
Tremor (1 paper, 2025). An unintentional, oscillating to-and-fro muscle movement about a joint axis. "ANK3 exon 1b‐null mice developed distinctive cerebellar defects, including abnormal gait, tremor, and reduced locomotion." (PMID 40879451, 2025).
ZIKV infection (1 paper, 2025). "Since AIS and nodes of Ranvier are essential for action potential initiation and propagation, it is conceivable that the simultaneous reduction of Ank3, Sptbn1, and Epb41l3 due to ZIKV infection can alter functions and structures of these excitable axonal domains." (PMID 39848964, 2025).
psychiatric disorder (23 papers, 2012 to 2024). A disorder characterized by behavioral and/or psychological abnormalities, often accompanied by physical symptoms. "ANK3 (ankyrin 3) encodes a variety of ankyrin-G isoforms, which play an important role in neural development and are well-explored in psychiatric disorders." (PMID 35988113, 2022). "Their top gene was Ank3, a gene with a strong association for psychiatric disorders; and they also demonstrated an interaction between functional genetic variants within Ank3 gene and obstetric complications on working memory in humans." (PMID 29192656, 2018). "We identified Ankyrin-3 (Ank3), a scaffolding protein with a strong genetic association for psychiatric disorders, as a gene persistently affected by stress exposure." (PMID 27824361, 2016). "The association between ANK3 and BD has since been replicated in multiple follow-up GWASs, identifying a range of additional SNPs to further confirm the link between ankyrin-G and psychiatric disease." (PMID 35794211, 2022). "We then examined methylation in a shortlist of genes that were previously associated with early life stress and psychiatric disorders as well as placental functioning: Ank3, Avp, Avpr1a, Avpr1b, Bdnf, Cacna1c, Cyp11b1, Cyp11b2, Fkbp5, Hsd11b1, Igf2, Morc1, Nr3c1, Oxt, Oxtr, Pclo, Slc6a4." (PMID 30655507, 2019). "Given the extent of this evidence for ANK3 impacting brain function, investigating the neural circuits and processes that it regulates is fundamentally important to understanding the abnormalities underlying BD and perhaps other mental illnesses." (PMID 23025490, 2012). "Animal and human studies have also demonstrated that early life stress may alter the methylation status of ANK35, with behavioral correlates, further pointing to ANK3 expression as a candidate moderator of early life stress effects in psychiatric diseases." (PMID 37620394, 2023). "In the present study, using a ‘converging evolutionary' approach, we identified an association between the exposure to ELS and the methylation status of Ank3 gene, which may support its role in the vulnerability to psychiatric disorders." (PMID 27824361, 2016). "Second, the actual effect of rs10994336 polymorphism on ANK3 methylation in brain tissues in which the pathological processes for psychiatric disorder are likely involved could not be directly observed in our study, since brain tissues are not readily accessible in living patients." (PMID 34421516, 2021). "Indeed, by investigating an Ank3 single-nucleotide polymorphism, rs9804190, which has previously been associated with heightened risk for different psychiatric disorders, we found that the C allele predicts lower post-mortem prefrontal Ank3 expression in non-psychiatric subjects." (PMID 27824361, 2016). "Our data suggest that alterations of Ank3 expression and function may contribute to the effects of ELS on the development of psychiatric disorders." (PMID 27824361, 2016). "The results in humans at the imaging and behavioral level, together with those obtained by our methylation analysis, suggest that Ank3 may represent an important link between ELS and the development of psychopathology, through alterations in neuronal circuits relevant for psychiatric diseases." (PMID 27824361, 2016).
cancer (18 papers, 2011 to 2026). A tumor composed of atypical neoplastic, often pleomorphic cells that invade other tissues. "The mutation rates of different MHGs varied widely across cancer tissues, with ANK3 having the highest mutation rate (47%), followed by KEL (18%), TRPM7 (16%), KCNA1 (13%), CNNM2 (9%), CNNM1 (9%), TFAP2B (9%), CNNM4 (9%), XK (7%), and EDN3 (5%)." (PMID 41174507, 2025). "Here, we observed that fusion with CCDC6 was associated with strong overexpression of ANK3 in all three cancers." (PMID 33097743, 2020). "ANK3, which encodes an immunospecific member of the ankyrin family, is widely expressed across nephron segments and functions as a tumor suppressor in multiple cancer types." (PMID 40821775, 2025). "Ankyrin 3 (ANK3) is a scaffold protein that plays important roles in maintaining physiological function of the kidney and its alteration is implicated in many cancers." (PMID 37423640, 2023). "The results showed that the expression of ANK3 (in the proteoglycans in cancer pathway), CDH3, and CNTNAP2 (in the cell adhesion molecule pathway) was downregulated." (PMID 35745623, 2022). "One study reported that ANK3 appeared to be downregulated in several human cancer types, thereby contributing to a poor prognosis." (PMID 35646694, 2022). "ANK3 plays a key role in cell motility and proliferation, and its down-regulation promotes cancer cell invasion." (PMID 29050228, 2017). "The findings that ANK3 and CNNM2 are low expressed in various cancers and associated with better survival outcomes suggest that these genes may serve as useful prognostic biomarkers." (PMID 41174507, 2025). "Novel recurrent cases were also found in ovarian (n = 6), endometrial (n = 2) and breast (n = 2) cancers involving CCDC6, a coiled-coil domain protein, fusing with ANK3 at the 3′ end, which encodes the ankyrin G protein that plays a key role in cell proliferation, as result of tandem duplications." (PMID 33097743, 2020). "Deregulation of ANK3 expression has been observed in multiple human cancers, and, while it contributes to poor prognosis, its mechanism remains unknown." (PMID 30941304, 2019). "In addition, we found some hypermethylated genes with an associated decrease in expression, such as ANK3, TSPYL5, RAB3A and ABCA2 that have been reported to be related with cancer or central nervous system diseases." (PMID 29221210, 2017). "In several human cancer types, ANK3 appeared to be down-regulated contributing to a poor prognosis." (PMID 26652480, 2015).